GOLGA6B (golgin A6 family member B)
Tractability: No criterion of Open Targets' tractability assessment is met for any kind of drug.
Gene: Protein-coding gene on chromosome 15 (72,654,697 to 72,669,599, forward strand). Ensembl gene ENSG00000215186.
Subcellular location (Human Protein Atlas): Vesicles; Centrosome; Nucleoplasm
Gene Ontology:
Biological process: Golgi organization
Cellular component: cis-Golgi network; Golgi cis cisterna; Golgi cisterna membrane; Golgi apparatus
Genetic constraint (gnomAD): Loss-of-function variants: 10 observed, 23.35 expected, observed/expected ratio (o/e) 0.43, 90% interval 0.26 to 0.73. The synonymous counts are far from expectation, so gnomAD's model fits this gene poorly and the ratio says little. Missense variants: 120 observed, 219.26 expected, observed/expected ratio (o/e) 0.55, 90% interval 0.47 to 0.64. Synonymous variants: 42 observed, 84.07 expected, observed/expected ratio (o/e) 0.5, 90% interval 0.39 to 0.65.
Homologues: Orthologues: mouse Golga2 (47% identical), dog GOLGA2 (45% identical), tropical clawed frog golga2 (34% identical), zebrafish golga2 (32% identical), Drosophila melanogaster GM130 (23% identical), Caenorhabditis elegans golg-2 (19% identical), rat Golga2l1 (5% identical). Paralogues in human: GOLGA6A (99% identical), GOLGA6C (99% identical), GOLGA6D (99% identical), GOLGA2 (55% identical), GOLGA8G (54% identical), GOLGA8F (52% identical), GOLGA8S (51% identical), GOLGA8N (49% identical), GOLGA8O (49% identical), GOLGA8Q (49% identical), GOLGA8T (48% identical), GOLGA8K (48% identical), and 6 more.
Diseases named in the same sentence as GOLGA6B in open-access papers:
GOLGA6B is named in the same sentence as 2 diseases in open-access papers, as found by Europe PMC text mining. Sharing a sentence is not in itself a finding about the gene and the disease.
GOLGA6B shares sentences with these, for which no sentence is quoted: cancer (1 paper); Prader-Willi syndrome (1).